GSDME (gasdermin E)
Diseases named in the same sentence as GSDME in open-access papers (continued):
Sharing a sentence is not in itself a finding about the gene and the disease.
cancer (continued). "Studies in the past decade have revealed frequent GSDME promoter hypermethylation in a variety of cancers, including breast, gastric, and colorectal tumors." (PMID 41550939, 2025). "What’s more, a recent study has revealed that metformin can trigger Caspase3/GSDME-mediated pyroptosis of cancer cells by activating the AMPK/SIRT1/NF-κB pathway." (PMID 40894196, 2025). "This subsequently activated the stimulator of interferon gene (STING) pathway, triggered ferroptosis, and induced gasdermin E (GSDME) mediated pyroptosis in cancer cells." (PMID 41144149, 2025). "Subsequently, by using The Cancer Genome Atlas (TCGA) and Gene Expression Omnibus (GEO) databases, GSDME expression was found to be significantly upregulated in cancer tissues from HCC patients." (PMID 39526199, 2024). "Several cancer cell lines were screened for GSDME expression, and SH-SY5Y and A549 cell lines were selected due to their GSDME expression and sensitivity to etoposide, facilitating the induction of pyroptosis." (PMID 39667498, 2024). "Recently, Gasdermin E (GSDME), another member of the pyroptosis family, was found to trigger pyroptosis in a variety of cancer cells." (PMID 38643134, 2024). "Although GSDME is found only in a limited subset of cancer cells, it plays a pivotal role in modulating the immune environment within tumors, promoting a robust T-cell-driven counter-cancer immune response." (PMID 38304430, 2024). "Paclitaxel has been widely used in cancer treatment; it induces caspase 3 activation and GSDME cleavage in a time-dependent manner in lung cancer." (PMID 39584140, 2024). "Emerging research findings have demonstrated that chemotherapy can trigger the activation of Caspase 3, leading to the cleavage of GSDME and the subsequent generation of N-GSDME, ultimately culminating in pyroptosis of cancer cells." (PMID 38902235, 2024). "In mice, ectopic GSDME expression in Gsdme-repressed tumors inhibited tumor growth mediated by Granzyme B in killer cytotoxic lymphocytes, which cleaved and activated GSDME in target cancer cells, leading to caspase-independent pyroptosis." (PMID 38195694, 2024). "Enhanced levels of PLK2 correlated with high levels of caspase-3 and GSDME cleavage, a hallmark of pyroptosis, in IFN treated USP18-/- cancer cells." (PMID 38799433, 2024). "In most cancer tissues, including breast, colorectal, gastric, and bladder tissues, GSDME is expressed at lower levels than in normal tissues." (PMID 39526199, 2024). "Members of the GSDM superfamily are proteolytically activated also by the CASP4/5/11 and CASP3/GSDME signaling pathway, which is a “switch” that can shift the balance between apoptosis and pyroptosis in cancer." (PMID 38994937, 2024). "Several studies have shown that chemotherapeutic drugs can activate GSDME, resulting in the stimulation of pyroptosis in cancer cells and the induction of antitumor immunity." (PMID 38169676, 2024). "Limited data from public databases indicate a positive correlation between CAF infiltration and the expression of GSDMD and GSDME in cancer cells, suggesting the potential for CAF-induced pyroptosis in cancer cells." (PMID 38649701, 2024). "GSDME, as one of the members of the Gasdermin family, is initially reported in cancer cell lines where it mediates pyroptosis after being cleaved by caspase-3." (PMID 38172670, 2024). "In this concern, during the treatment of malignant tumors, specific chemotherapeutic drugs can be selected based on the expression levels of GSDME." (PMID 38994937, 2024). "Sp1 increases GSDME expression to ensure pyroptosis occurs during cancer cells stimulated by chemotherapy drugs, consistent with the previous report that the expression of GSDME is essential to the apoptosis-to-pyroptosis switch." (PMID 38238307, 2024).
cancer (continued). "GSDME knockdown converts pyroptosis into apoptosis, decreases invasion and migration and enhances the sensitivity of carcinoma cells to chemotherapy." (PMID 39616223, 2024). "It has also been shown that the promoter region of GSDME is highly methylated in a variety of cancers." (PMID 37208730, 2023). "In cancer cell lines, caspase-3 can specifically cleave GSDME to induce a switch from apoptosis to pyroptosis, enhancing the sensitivity of cancer cells to chemotherapeutic agents." (PMID 38104141, 2023). "Recently, the cleavage of GSDME by caspase three was also reported to be one of the most critical signalings in forming pyroptosis in cancer." (PMID 37528490, 2023). "GSDME-mediated pyroptosis has been observed to improve the sensitivity of various drugs across different cancer types, including increasing DDP sensitivity in esophageal squamous cell carcinoma cells and oxaliplatin sensitivity in colon cancer cells." (PMID 38239395, 2023). "In a recent study, it was discovered that GSDME methylation is prevalent in various cancer types, with extensive hypermethylation in promoter and gene body CpGs." (PMID 38104141, 2023). "The Cancer Genome Atlas (TCGA) bulk RNA-seq data also showed that the mRNA expression level of GSDME in cancer tissues is lower than that in normal tissues (TCGA-pan cancer)." (PMID 37208730, 2023). "When GSDME was overexpressed, it resulted in a decrease in cancer cell proliferation, migration, colony formation and invasion, while its decrease had the opposite effect." (PMID 37705746, 2023). "Enhanced levels of PLK2 correlated with high levels of GSDME cleavage, a hallmark of pyroptosis, in IFN-treated USP18−/− THP-1 and MDA-MB-231 cancer cells." (PMID 36646704, 2023). "Anti-cancer drugs, such as pacisplatin, Lobaplatin, and triptolide, induce pyroptosis through the GSDME/caspase-3 pathway." (PMID 37705746, 2023). "The released granzyme B and perforin trigger caspase‐3/GSDME‐induced cancer cell pyroptosis to achieve CAR‐T‐cell cancer therapy." (PMID 37125240, 2023). "Granzyme B secreted by NK cells cleaves GSDME directly or activates caspase‐3 to cleave GSDME indirectly, inducing the pyroptosis of GSDME‐expressing cancer cells." (PMID 37125240, 2023). "This pathway promotes the build-up of Bax and the release of cytochrome c, ultimately resulting in the activation of caspase 3 and the cleavage of gasdermin E (GSDME) in cancer cells." (PMID 37175631, 2023). "GSDME has been extensively studied in the field of cancer biology; however, its function in the central nervous system has yet to be elucidated." (PMID 36670138, 2023). "Despite being silenced in most cancer cells, GSDME is expressed in many normal tissues, such as the brain, heart, gastrointestinal tract, and hematopoietic cells." (PMID 38104141, 2023). "We further analyzed GSDME expression using the GEPIA database and found aberrant expression of GSDME in 33 human cancers." (PMID 37679782, 2023). "All of this evidence suggests an unexpected conclusion that Cas-3 activation can activate pyroptosis by cutting GSDME, which opens up a new picture for chemotherapy drug treatment of cancer." (PMID 37542066, 2023). "After chemotherapy, the drug-induced cleavage of GSDME by caspase-3 would mediate apoptosis into pyroptosis in some cancer cells expressing GSDME." (PMID 36979404, 2023). "It is noteworthy that the caspase-3/GSDME signaling pathway can behave as a switch between pyroptosis and apoptosis in cancer." (PMID 37627547, 2023). "Previous studies had revealed that caspase-3 activation specifically cleaved GSDME to induce pyroptosis in cancer cells." (PMID 37169767, 2023). "For instance, cancer cells with highly expressed GSDME protein were dominantly undergoing pyroptosis upon the death signals, while GSDME-low cancer cells underwent apoptosis." (PMID 37528490, 2023).
cancer (continued). "Nowadays, the caspase-1/GSDMD and caspase-3/GSDME pathways have attracted significant attention in pyroptosis induction, and many natural compounds have been found to activate these pathways in cancers." (PMID 38239395, 2023). "A tumor-growth-suppressor function has been proposed for GSDME, based on the observation that a decrease in the expression of this gasdermin correlates, in certain cancers, with a decreased survival, as it activates antitumor immunity." (PMID 37627547, 2023). "GSDME is cleaved by caspase-3 downstream of caspase-8 in cancer cells, intestinal epithelial cells, and macrophages." (PMID 37279255, 2023). "Hence, cancer cells expressing high leveled GSDME may be more susceptible to pyroptosis." (PMID 37208730, 2023). "Inhibiting DNA methylation will upregulate the expression of GSDME and improve the killing potential of chemotherapy drugs against cancer cells." (PMID 37208730, 2023). "Caspase-3, the executor in apoptosis, can activate gasdermin E (GSDME/DFNA5) in cancer cells receiving chemotherapy; in contrast, it inactivates GSDMD by cleaving it at D88 sites (destroying the N-terminal pore formation structure)." (PMID 37895022, 2023). "On the other hand, the released DAC upregulates GSDME expression via suppressing DNA methylation, leading to powerful cancer cell pyroptosis." (PMID 36823153, 2023). "Scientists have stated that GSDME is expressed at low levels in the majority of cancer cells because of promoter hypermethylation in tumors." (PMID 38016064, 2023). "We found that most tumors analyzed and exhibited a certain level of GSDMs expression; however, the expression of GSDMD, GSDMB, and GSDME in pan-cancers was markedly higher than that of other genes." (PMID 36003332, 2022). "Since GSDME-mediated pyroptosis has emerged as a new cancer treatment strategy, we focused on the mechanism of BI 2536-induced pyroptosis." (PMID 36016611, 2022). "Targeting pyroptosis is considered a novel enrichment to our cancer-fighting arsenal and GSDME is the newly recognized executor of pyroptosis." (PMID 35517821, 2022). "Chemotherapy drugs can initiate caspase-3-mediated apoptosis in cancer cells, but the process will be switched to pyroptosis with abundant GSDME expression." (PMID 36209102, 2022). "Loss of GSDME or caspase-3 significantly attenuated GSDME-dependent pyroptosis in A549, PC9, or NCI-H3122 cancer cells." (PMID 36523974, 2022). "Together, a comprehensive understanding of GSDME function in different types of cancer is worthy of further investigation." (PMID 36376979, 2022). "Studies have used hypomethylating agents such as decitabine (DAC) or 5-aza-2′-deoxycytidine (5-Aza-CdR) to restore the transcription of the GSDME gene and reinstate the sensitivity of various cancer cells, including GC cells, to chemotherapy." (PMID 35517821, 2022). "GSDME has been shown to be involved in tumorigenesis and by mediating pyroptosis in a variety of cancers." (PMID 36338707, 2022). "Once activation by chemotherapy drugs, caspase-3 mediates the cleavage of GSDME in GSDME-expressing cancer cells to liberate its N-terminal domain (GSDME-N), hence inducing cancer cell pyroptosis." (PMID 36387211, 2022). "A study has reported that metformin activates the NF-κB signaling pathway to drive caspase-3/GSDME-mediated pyroptosis in cancer cells." (PMID 35309514, 2022). "Several classical chemotherapy drugs including cisplatin, paclitaxel, 5-fluorouracil, and doxorubicin (DOX) was also reported to induce caspase-3/GSDME-modulated pyroptosis in various cancer cells." (PMID 36119049, 2022). "The results showed that the expression levels of IL-6, IL18 and GSDME were positively associated with these compounds, while CASP4 was positively correlated with sensitivity to 26 cancer drugs." (PMID 35246158, 2022). "Elevation of GSDME cleavage in our study suggests that the drug combination is related to cancer immunotherapy." (PMID 36058938, 2022).
cancer (continued). "On the contrary, in various tumors with high GSDME expression, chemotherapeutic drug-mediated pyroptosis is recognized as a powerful weapon to induce cancer cell death." (PMID 35693810, 2022). "In cancer cells with high expression of GSDME, caspase-3 specifically cleaves GSDME to convert apoptosis into pyroptosis." (PMID 36091247, 2022). "After chemotherapeutic treatment, caspase-3-induced cleavage of GSDME determines cellular pyroptosis in some GSDME-expressing cancer cells." (PMID 36091790, 2022). "DFNA5 (GSDME) belongs to Gasdermin familily that is involved in a variety of cancers and triggers cell pyroptosis after chemical treatment." (PMID 35248047, 2022). "In cancer, pyroptosis has been shown to be triggered by almost all signaling pathways in which GSDME, GSDMD, GSDMC, or GSDMB serve as the executors." (PMID 35673561, 2022). "Mouse and human studies have pointed towards a role of GSDME in cancer tumorigenesis to such an extent that GSDM expression has been proposed as a biomarker for prognosis and response to treatment." (PMID 35844522, 2022). "Subsequently, a series of studies suggested that it is a common phenomenon that GSDME expression is lower in most cancer cells than in normal cells due to the epigenetic inactivation caused by methylation." (PMID 35462927, 2022). "PRGs with consistent enhanced expression and association with poor survival in cancers included GSDMC in BRCA, KIRC, LIHC, PAAD, UVM and KICH; DFNA5 (GSDME) in COAD, STAD, UCEC, HNSC, KIRC; and AIM2 in KIRP, KIRC, UVM, and PAAD." (PMID 36605187, 2022). "It is reported that these drugs can increase GSDME expression and sensitize the cancer cells to chemotherapy drug by inducing GSDME-mediated pyroptosis." (PMID 36209102, 2022). "Wang’s research indicates that cancer cells treated with chemotherapeutic drugs can undergo apoptosis and pyroptosis, due to the primary expression of GSDME." (PMID 35123387, 2022). "Decitabine, a DNA methylation inhibitor drug which can upregulate GSDME expression in several cancers and increase their sensitivity to chemotherapy drug-induced pyroptosis, is undoubtedly a promising candidate." (PMID 36209102, 2022). "The caspase-GSDME pathway is usually related to the production of intracellular reactive oxygen species (ROS) in cancer cells." (PMID 36248872, 2022). "Upon treatment with chemotherapeutic drugs, GSDME is activated by caspase-3, resulting in pyroptosis of cancer cells with high GSDME expression." (PMID 35462927, 2022). "Increased levels of intracellular ROS and caspase-3 were able to initiate GSDME-mediated pyroptosis in cancer." (PMID 36387211, 2022). "Studies in vitro determined that the overexpression of GSDME significantly reduced the cell proliferation, colony formation and invasion capacity of cancer cells, whereas downregulation of GSDME significantly enhanced these activities." (PMID 35462927, 2022). "It has been shown that the key pyroptotic proteins GSDMB and GSDME/DFNA5 can be cleaved by granzymes, especially granzymes A and B, respectively, to induce pyroptosis in cancer cells." (PMID 35300338, 2022). "Only HepG2 and 446 cancer cells had very few GSDME cleavage protein bands, while the other seven cells did not undergo pyroptosis." (PMID 35002520, 2022). "Promoter DNA methylation inactivates GSDME in many cancer cells resulting in low levels of GSDME expression." (PMID 35677444, 2022). "As a further barrier to pyroptosis, GSDME is also repressed in the context of cancer; it has been shown to be detectable in only ~10% of human cancer cell lines (5 of 60 lines tested in the NCI-60 panel)." (PMID 35592329, 2022). "The expression of GSDME varies in different cancers and is mainly activated by apoptotic caspase-3 and caspase-8." (PMID 35673561, 2022). "We next analyzed the association between expression of GSDME and the VEGF in Cancer Cell Line Encyclopedia (CCLE)." (PMID 35164740, 2022).
cancer (continued). "This study showed that GSDME-mediated pyroptosis is a novel mechanism for eradicating cancer cells using lobaplatin, which is of great significance for clinical applications." (PMID 35673561, 2022). "Although expressed in many healthy tissues, GSDME can be effectively silenced in the context of cancer by promoter methylation, and expression can be restored through a methyltransferase inhibitor." (PMID 35592329, 2022). "Pan-cancer analysis revealed that GSDME was highly expressed in most malignancies and significantly correlated with patients' survival." (PMID 35432539, 2022). "As representatives of radiosensitive tumors, NPC cells universally exhibited higher GSDME expression than other cancer cells." (PMID 36411454, 2022). "At the same time, ROS are key molecules that induce GSDME-mediated pyroptosis, and their elevation stimulates the cleavage of casp-3 and GSDME in cancer cells, thereby inducing pyroptosis." (PMID 36551691, 2022). "Noticeably, the high expression of GSDME was significantly (FDR < = 0.05) correlated with EMT activation in 41% of cancer types." (PMID 35164740, 2022). "A new synthesized ligand TFBIP and its three iridium (III) complexes were found to induce GSDME-mediated pyroptosis, thus decreasing cell viability in several cancers." (PMID 36209102, 2022). "DCT molecules synergistically facilitated the expression of GSDME through DNA methylation, which contributed to caspase-3 cleavage and induced stronger cancer pyroptosis." (PMID 34976215, 2022). "Previous studies convincingly demonstrated that GSDME mRNA methylation resulted in GSDME downregulation in various cancers, and downregulated GSDME levels were related with decreased survival rate in BRCA." (PMID 35646948, 2022). "First, although bioinformatic analysis offered us some significant insights of GSDME in cancers, it is necessary to conducted biological experiments in vitro or in vivo for checking on our findings and accelerating clinical application." (PMID 34381728, 2021). "Recent studies indicated that chemotherapy drug–activated caspase-3 can also induce secondary necrosis/pyroptosis in both cancer and normal cells with expression of gasdermin E (GSDME), a member of the gasdermin family." (PMID 34305590, 2021). "Diverse small-molecule inhibitors have also been shown to augment the anti-cancer effect by inducing GSDME cleavage." (PMID 33589596, 2021). "Since its discovery in 1998, a large number of studies have revealed the potential implication of GSDME in cancer." (PMID 33634141, 2021). "It has been found that GSDME-mediated pyroptosis induced cancer cells proliferation and PCNA(proliferating cell nuclear antigen) expression through the ERK1/2 pathway by releasing intracellular HMGB1, which in turn promoted the development of CAC." (PMID 34381721, 2021). "Our research, for the first time, explored the potential carcinogenic role of GSDME across 33 tumors from the public platform of TCGA (The cancer genome atlas) database." (PMID 34381728, 2021). "Further studies that unveil GSDME biological functions will improve the current understanding of its role in cancer proliferation and invasion, which will expedite the development of novel anti-cancer therapies." (PMID 34335940, 2021). "The effect of GSDME, a newly defined executor of pyroptosis, has recently been reported in various cancers, with strategies targeting GSDME proposed to block pyroptosis." (PMID 33589596, 2021). "Nevertheless, GSDME can still be considered a potential target for these types of cancer with high GSDME expression." (PMID 34522213, 2021). "In summary, our pan-cancer analysis of GSDME not only broadens understanding of the carcinogenic roles of GSDME, but also provides a promising therapeutic strategy for benefiting an increasing number of cancer patients based on GSDME-induced pyroptosis." (PMID 34381728, 2021).